PINK1 (PTEN induced kinase 1)
Description:
Serine/threonine-protein kinase which acts as a sensor of mitochondrial damage and protects against mitochondrial dysfunction during cellular stress. It phosphorylates mitochondrial proteins to coordinate mitochondrial quality control mechanisms that remove and replace dysfunctional mitochondrial components. In healthy mitochondria, PINK1 is translocated across the mitochondrial outer membrane (MOM) via the translocase of the outer membrane (TOM) complex, and inserted into the mitochondrial inner membrane (MIM) via the translocase of the inner membrane (TIM23) complex where it is cleaved and released into the cytosol. Depending on the severity of mitochondrial damage, activity ranges from preventing apoptosis and stimulating mitochondrial biogenesis to eliminating severely damaged mitochondria via PINK1-PRKN-dependent mitophagy. When cellular stress results in irreversible mitochondrial damage, PINK1 accumulates at the outer mitochondrial membrane (OMM) where it phosphorylates pre-existing polyubiquitin chains at 'Ser-65', recruits PRKN from the cytosol to the OMM and activates PRKN by phosphorylation at 'Ser-65'; activated PRKN then ubiquitinates VDAC1 and other OMM proteins to initiate mitophagy. The PINK1-PRKN pathway also promotes fission of damaged mitochondria through phosphorylation and PRKN-dependent degradation of mitochondrial proteins involved in fission such as MFN2. This prevents the refusion of unhealthy mitochondria with the mitochondrial network or initiates mitochondrial fragmentation facilitating their later engulfment by autophagosomes. Also promotes mitochondrial fission independently of PRKN and ATG7-mediated mitophagy, via the phosphorylation and activation of DNM1L. Regulates motility of damaged mitochondria by promoting the ubiquitination and subsequent degradation of MIRO1 and MIRO2; in motor neurons, this likely inhibits mitochondrial intracellular anterograde transport along the axons which probably increases the chance of the mitochondria undergoing mitophagy in the soma. Required for ubiquinone reduction by mitochondrial complex I by mediating phosphorylation of complex I subunit NDUFA10 (By similarity). Phosphorylates LETM1, positively regulating its mitochondrial calcium transport activity.
Synonyms: BRPK; PARK6
Tractability: Small molecule: a structure with a bound ligand is known; a high-quality ligand is known; it belongs to a druggable protein family. Antibody: UniProt predicts a signal peptide or a membrane-spanning region. PROTAC: ubiquitination databases record sites on it; a small molecule that binds it is known.
Target class: Kinase; Enzyme; Protein Kinase
Gene: Protein-coding gene on chromosome 1 (20,633,458 to 20,651,511, forward strand). Ensembl gene ENSG00000158828.
Subcellular location: Mitochondrion outer membrane; Mitochondrion inner membrane; Cytoplasm, cytosol
Pathways (Reactome):
Autophagy: PINK1-PRKN Mediated Mitophagy
Gene expression (Transcription): FOXO-mediated transcription of cell death genes
Gene Ontology:
Molecular function: ATP binding; C3HC4-type RING finger domain binding; kinase activity; kinase binding; magnesium ion binding; protease binding; protein binding; protein kinase activity; protein kinase B binding; protein serine kinase activity; protein serine/threonine kinase activity; protein-containing complex binding; ubiquitin protein ligase binding; peptidase activator activity
Biological process: autophagy of mitochondrion; cellular response to hypoxia; cellular response to oxidative stress; hemopoiesis; intracellular signal transduction; maintenance of protein location in mitochondrion; mitochondrion organization; mitochondrion to lysosome vesicle-mediated transport; mitophagy; negative regulation of autophagosome assembly; negative regulation of hydrogen peroxide-induced neuron intrinsic apoptotic signaling pathway; negative regulation of intrinsic apoptotic signaling pathway; negative regulation of intrinsic apoptotic signaling pathway in response to hydrogen peroxide; negative regulation of macroautophagy; negative regulation of mitochondrial fission; negative regulation of mitophagy; negative regulation of neuron apoptotic process; negative regulation of oxidative stress-induced neuron intrinsic apoptotic signaling pathway; negative regulation of reactive oxygen species metabolic process; positive regulation of canonical NF-kappaB signal transduction; positive regulation of cell migration; positive regulation of cristae formation; positive regulation of establishment of protein localization to mitochondrion; positive regulation of macroautophagy; positive regulation of phosphatidylinositol 3-kinase/protein kinase B signal transduction; and 43 more
Cellular component: astrocyte projection; axon; cell body; chromatin; cytoplasm; cytoskeleton; cytosol; endoplasmic reticulum; membrane; mitochondrial inner membrane; mitochondrial intermembrane space; mitochondrial outer membrane; mitochondrion; nucleus; perinuclear region of cytoplasm; Lewy body; growth cone
Genetic constraint (gnomAD): Loss-of-function variants: 58 observed, 54.93 expected, observed/expected ratio (o/e) 1.06, 90% interval 0.85 to 1.31. The upper end of that interval is the gene's LOEUF score, 1.31, which puts it in group 5 of 6, group 1 being the genes least tolerant of losing a copy. Missense variants: 745 observed, 754.97 expected, observed/expected ratio (o/e) 0.99, 90% interval 0.93 to 1.05. Synonymous variants: 354 observed, 322.83 expected, observed/expected ratio (o/e) 1.1, 90% interval 1 to 1.2.
Gene-disease validity (ClinGen):
ClinGen rates the evidence that PINK1 causes each of these diseases.
Parkinson disease (autosomal recessive): Definitive. A progressive degenerative disorder of the central nervous system characterized by loss of dopamine producing neurons in the substantia nigra and the presence of Lewy bodies in the substantia nigra and locus coeruleus.
Homologues: Orthologues: chimpanzee PINK1 (99% identical), macaque PINK1 (97% identical), dog PINK1 (88% identical), pig PINK1 (88% identical), guinea pig PINK1 (83% identical), rat Pink1 (82% identical), mouse Pink1 (81% identical), rabbit PINK1 (78% identical), zebrafish pink1 (53% identical), Drosophila melanogaster Pink1 (31% identical), Caenorhabditis elegans pink-1 (27% identical). Paralogues in human: PEAK1 (23% identical), PRAG1 (22% identical), PEAK3 (13% identical).
Diseases named in the same sentence as PINK1 in open-access papers:
PINK1 is named in the same sentence as 359 diseases in open-access papers, as found by Europe PMC text mining. Sharing a sentence is not in itself a finding about the gene and the disease. The quoted sentences say what the papers report.
Parkinson disease (793 papers, 2005 to 2026). "Parkinson's disease-associated proteins PINK1 and Parkin collaboratively regulate stress-induced mitophagy." (PMID 42317396, 2026). "Central to this process are PINK1 and Parkin, two Parkinson’s disease-associated proteins that orchestrate the polyubiquitination of damaged mitochondrial surface proteins to initiate autophagic clearance." (PMID 40918504, 2025). "Dysregulation of PINK1 signaling has been linked to neurodegenerative diseases such as Parkinson’s disease, autosomal recessive juvenile parkinsonism and amyotrophic lateral sclerosis, and is a topic of intense study." (PMID 40442372, 2025). "Mitophagy mediated by PINK1/Parkin is also associated with neurodegenerative diseases such as Alzheimer's disease and Parkinson's disease." (PMID 40016173, 2025). "The PINK1/Parkin pathway, originally linked to Parkinson’s disease, is crucial for mitochondrial clearance." (PMID 39859167, 2025). "This impairment is particularly relevant in Parkinson’s disease, where mutations in PINK1 and PARKIN affect both mitophagy and MDV formation." (PMID 41008559, 2025). "Secondly, Cluster#2, "Intracellular Organelle" is influenced by several clusters, including "Pink1-associated Parkinson's Disease", "Mitochondrial Dynamics", "SQSTM1 Cooperation", "Mitochondrial Fission" and "Small N-terminal Tag"." (PMID 41267150, 2025). "It plays a central role in the regulation of the PINK1/Parkin pathway, which is not only implicated in Parkinson's disease (discussed more in depth under pathological roles below), but also in adipocyte differentiation." (PMID 41015904, 2025). "For instance, the PINK1–Parkin pathway has been implicated in early-onset Parkinson’s disease, with loss-of-function recessive mutations in PINK1 or Parkin being the most common cause of the disease under 50 years old." (PMID 40680837, 2025). "Defective mitochondrial quality control in response to loss of mitochondrial membrane polarization is implicated in Parkinson’s disease by mutations in PINK1 and PRKN." (PMID 40196634, 2025). "Loss of function, autosomal recessive mutations in PINK1 are known to cause early onset Parkinson’s disease (EOPD), leading to the onset of symptoms, including tremor, rigidity, and bradykinesia, at a mean age of 31 years old5,6." (PMID 41279391, 2025). "Defective mitochondrial quality control is linked to Parkinson’s disease via mutations in the genes PINK1 and PRKN." (PMID 40743392, 2025). "PRKN and PINK1 gene mutations have been associated with Parkinson's disease (PD), particularly early‐onset PD (EOPD)." (PMID 40898742, 2025). "In experimental models, Parkin knockout (Parkin−/−) and PINK1 knockout (PINK1−/−) mice exhibit progressive mt dysfunction, leading to the loss of dopaminergic neurons, a key feature of Parkinson's disease." (PMID 40418056, 2025). "PARL is a key regulator of the PINK1‐Parkin pathway, a major axis associated with the pathogenesis of Parkinson's disease (PD)." (PMID 41015904, 2025). "Monogenic disorders of mitophagy with PINK1 or Parkin/PRKN deficiency are associated with early‐onset parkinsonism in humans." (PMID 41053928, 2025). "Strikingly, both Mirana and Pink1, whose loss in humans causes Parkinson’s disease, appear to be specifically required during development for mitochondrial size regulation and DCN circuit wiring." (PMID 40890095, 2025). "For instance, genes such as SNCA (encoding α-synuclein), SIAH2, HSPA1A (encoding HSP-70), and PINK1 are upregulated in children with CM, mirroring the molecular dysregulation observed in Parkinson’s and Alzheimer’s diseases." (PMID 40149586, 2025). "Background and aims: Homozygous deletions in PARK2 and PINK1 are both associated with autosomal recessive forms of Parkinson's disease (PD)." (PMID 40542608, 2025).
Parkinson disease (continued). "Mitochondria are often targeted for degradation by a process regulated by a sequence of phosphorylation and ubiquitination steps regulated by two genes that have been linked to Parkinson’s disease, PTEN-induced putative kinase 1 (PINK1) and Parkin." (PMID 40795095, 2025). "Mutations in PINK1 lead to an autosomal-recessive form of Parkinson’s disease (PD), probably through enhancing α-synuclein aggregation and reducing mitochondrial respiration and ATP production." (PMID 40650193, 2025). "In particular, the fly was instrumental in identifying and investigating the cellular functions of Parkinson disease’s genetic risk factors, PINK1 and PRKN (i.e. Pink1 and parkin in 21Drosophila)." (PMID 40236063, 2025). "In summary, the exploration of specific genetic mutations, such as those in LRRK2 and PINK1, provides valuable insights into the intricate landscape of Inherited Parkinson’s Disease." (PMID 40291849, 2025). "For example, mutations in the Parkin and PINK1 genes lead to early-onset Parkinson’s disease, with mechanisms involving defects in the PINK1/Parkin pathway that cause abnormal mitochondrial quality control." (PMID 41048372, 2025). "Familial early‐onset Parkinson's disease has been associated with biallelic PINK1 (PARK6) mutations and PARK2 gene functional loss, causing Parkin deficiency." (PMID 40356246, 2025). "The PINK1/PRKN pathway is closely associated with Parkinson’s disease and influences various cell processes in cancer cells." (PMID 39859167, 2025). "In Parkinson’s and Alzheimer’s diseases, mutations in PINK1, Parkin, and related genes upset this balance, leading to neurodegeneration." (PMID 41426598, 2025). "In some cases, mutations that are pathogenic in humans, such as those in the PINK1 and Parkin genes that cause Parkinson’s disease, fail to cause robust neurodegeneration in mice." (PMID 40344041, 2025). "A 51‐year‐old Chinese man with 27‐year early‐onset Parkinson's disease harbored rare PRKN/PINK1 mutations." (PMID 40898742, 2025). "Mutations in Parkin and PINK1 are associated with early onset Parkinson’s disease and have been shown in cell culture models to lead to impaired mitophagy." (PMID 38394123, 2024). "In support, Ret overexpression rescued muscle degeneration of the Pink1 deficient Drosophila model of Parkinson’s disease (PD) by restoring the mitochondrial respiratory complex I activity partly through upregulating mRNA expression of its subunit, NDUFV255." (PMID 38378752, 2024). "Genetic mutations and protein abnormalities linked to diseases like Alzheimer’s (APP, PSEN1, PSEN2), Parkinson’s (PINK1, LRRK2), and Huntington’s (HTT) can be detected in fibroblasts, reflecting similar changes in brain pathology." (PMID 39766775, 2024). "For example, in Parkinson’s disease, the recessive gene PINK1 is associated with monogenic forms of the condition." (PMID 39127776, 2024). "The ubiquitin kinase PINK1 accumulates on damaged mitochondria to trigger mitophagy, and PINK1 loss-of-function mutations cause early onset Parkinson’s disease." (PMID 38241364, 2024). "PINK1 loss-of-function mutations and exposure to mitochondrial toxins are causative for Parkinson's disease (PD) and Parkinsonism, respectively." (PMID 38765977, 2024). "Curiously, it also interacts with PINK1, which instigates mitophagy, and for which loss-of-function mutations are best described in Tunisian families with parkinsonism." (PMID 39062657, 2024). "The PINK1/Parkin pathway of mitophagy has been implicated in the pathogenesis of Parkinson’s disease." (PMID 38394123, 2024). "TOM70 also can regulate the immune system by engaging in the recruitment of PINK1 and the E3 ubiquitin ligase Parkin, playing a role in processes associated with Parkinson’s disease." (PMID 39264847, 2024). "PINK1, a mitochondrial-associated protein, has been identified as an autoantigen targeted by T cells from patients with Parkinson’s disease." (PMID 39688918, 2024).
Parkinson disease (continued). "Loss-of-function mutations in PTEN-induced putative kinase 1 (PINK1) cause Parkinson’s disease through physiological processes that have yet to be fully elucidated." (PMID 38416681, 2024). "The importance of the pathway is further underscored as complete loss of PINK1 or PRKN function are the most common causes of early-onset Parkinson’s disease (PD)." (PMID 40008113, 2024). "PINK1, mutated in familial forms of Parkinson’s disease, initiates mitophagy following mitochondrial depolarization." (PMID 38988500, 2024). "The most co-cited paper (503 citations) was “Hereditary early-onset Parkinson’s disease caused by mutations in PINK1,” published in the journal Science with an impact factor of 56.9." (PMID 39350973, 2024). "It has recently been shown that KAT8, a genome-wide association study candidate risk gene for Parkinson’s Disease, is involved in PINK1/Parkin-dependant mitophagy." (PMID 38777823, 2024). "Mutations in the mitochondrial-targeted kinase PINK1 and the E3 ubiquitin ligase Parkin cause familial forms of parkinsonism." (PMID 38273330, 2024). "Familial forms of Parkinson’s disease account for around 5–10% of all cases, and mutations in two genes, PINK1 and Parkin, mediate autosomal recessive forms of the disease." (PMID 38607086, 2024). "For instance, mutations in PRKN and PINK1 are often evident in patients with familial and sporadic Parkinson’s disease (PD)." (PMID 38678018, 2024). "The assembly of the autophagy initiation machinery nucleates autophagosome biogenesis, including in the PINK1- and Parkin-dependent mitophagy pathway implicated in Parkinson’s disease." (PMID 36791199, 2023). "PINK1/Parkin is a classic mitophagy pathway that was first found to be closely associated with Parkinson's disease in humans; however, growing evidence indicates that this pathway plays a role in other pathologic processes." (PMID 36625039, 2023). "The motor defects and mitochondrial dysfunction were successfully restored by PINK1 and parkin, which are Parkinson’s disease-associated genes that have critical roles in maintaining mitochondrial function and integrity." (PMID 36979812, 2023). "An illustration of this is the discovery of the PINK1–Parkin-dependent mitophagy pathway through initial genetic associations with familial early-onset recessive Parkinson’s disease (PD)." (PMID 37384773, 2023). "Parkin, an E3 ubiquitin ligase, and PINK1, a ubiquitin kinase, are involved in mitophagy function and are risk genes for early onset Parkinson’s disease (PD)." (PMID 37941028, 2023). "Mutations in the PRKN and PINK1 genes account for most of the recessive early-onset Parkinson’s disease (PD) cases." (PMID 36941054, 2023). "The mitochondrial quality control defects are also apparent in Parkinson’s disease (PD) patients having PINK1, DJ-1, and Parkin gene mutations." (PMID 36968195, 2023). "Signaling proteins such as PINK1 and Parkin are mutated in sporadic Parkinson’s disease, leading to an accumulation of dysfunctional mitochondria." (PMID 36986196, 2023). "While loss of either PINK1 or PRKN is genetically linked to Parkinson disease (PD) and activating the pathway seems to have great therapeutic potential, there is no formal proof that stimulation of mitophagy is always beneficial." (PMID 36469690, 2023). "Mutations in the PINK1 gene are an important cause of early-onset Parkinson’s disease (EOPD), accounting for 1–9% of genetic cases and 15% of early-onset cases—second only to Parkin mutations." (PMID 37445986, 2023). "For instance, in Parkinson’s disease, mutations in PINK1 and Parkin protein, which are crucial for maintaining mitochondrial health, are known to contribute to disease pathogenesis." (PMID 38002524, 2023). "The Parkinson’s disease (PD) gene family expression is strongly linked to tumor development and progression; PINK1 and PARK2 are essential members of the PD gene family." (PMID 37833780, 2023).